ENSG00000282218 (novel protein, GOPC-ROS1 readthrough)
Gene: Protein-coding gene on chromosome 6 (117,318,211 to 117,573,571, reverse strand). Ensembl gene ENSG00000282218.
Genetic constraint (gnomAD): Loss-of-function variants: 20 observed, 27.62 expected, observed/expected ratio (o/e) 0.72, 90% interval 0.51 to 1.05. Missense variants: 275 observed, 321.01 expected, observed/expected ratio (o/e) 0.86, 90% interval 0.77 to 0.95. Synonymous variants: 108 observed, 112.93 expected, observed/expected ratio (o/e) 0.96, 90% interval 0.82 to 1.12.